SPRR1A (small proline rich protein 1A)
Description:
Cross-linked envelope protein of keratinocytes. It is a keratinocyte protein that first appears in the cell cytosol, but ultimately becomes cross-linked to membrane proteins by transglutaminase. All that results in the formation of an insoluble envelope beneath the plasma membrane.
Synonyms: SPRK
Tractability: Antibody: its Gene Ontology location is reachable by antibodies, with high confidence.
Gene: Protein-coding gene on chromosome 1 (152,984,081 to 152,985,814, forward strand). Ensembl gene ENSG00000169474.
Subcellular location: Cytoplasm
Pathways (Reactome):
Developmental Biology: Formation of the cornified envelope
Gene Ontology:
Molecular function: protein binding; structural constituent of skin epidermis; structural molecule activity
Biological process: cornification; keratinocyte differentiation; peptide cross-linking; epidermis development
Cellular component: cornified envelope; cytosol; cytoplasm
Genetic constraint (gnomAD): Loss-of-function variants: 1 observed, 3.67 expected, observed/expected ratio (o/e) 0.27, 90% interval 0.095 to 1.26. That is too few expected variants to judge how well the gene tolerates losing a copy. Missense variants: 123 observed, 109.11 expected, observed/expected ratio (o/e) 1.13, 90% interval 0.97 to 1.31. Synonymous variants: 40 observed, 40.28 expected, observed/expected ratio (o/e) 0.99, 90% interval 0.77 to 1.29.
Homologues: Orthologues: pig SPRP (91% identical). Paralogues in human: SPRR1B (96% identical), SPRR3 (74% identical), SPRR4 (52% identical), SPRR2G (43% identical), KPLCE (31% identical), PRR9 (31% identical), LCE2B (26% identical), LCE2C (26% identical), LCE2D (26% identical), LCE1E (25% identical), LCE1F (25% identical), LCE2A (25% identical), and 8 more.
Diseases named in the same sentence as SPRR1A in open-access papers:
SPRR1A is named in the same sentence as 51 diseases in open-access papers, as found by Europe PMC text mining. Sharing a sentence is not in itself a finding about the gene and the disease. The quoted sentences say what the papers report.
melanoma (5 papers, 2008 to 2023). A malignant, usually aggressive tumor composed of atypical, neoplastic melanocytes. "We find that primary basal cell carcinomas, squamous cell carcinomas and thin melanomas express dramatically higher levels of many genes, including SPRR1A/B, KRT16/17, CD24, LOR, GATA3, MUC15, and TMPRSS4, than metastatic melanoma." (PMID 18442402, 2008). "The activation transcription factors, which regulate SPRR1A (small proline rich protein 1A), KRT78, claudin 4 and RAB25 (a member of the RAS oncogene family), also play crucial roles in malignant melanoma metastasis." (PMID 29377892, 2018). "We found LOR, EVPL, SPRR1A, FLG, DSP, and CSTA had been reported in previous studies on melanoma." (PMID 35003328, 2021).
breast carcinoma (4 papers, 2014 to 2022). "SPRR1A is known to play a role in various types of cancer, such as diffuse large B-cell lymphomas, head and neck squamous cell carcinoma, and breast cancer." (PMID 35740697, 2022). "Gain of 1q in cancer, specifically in breast cancer has previously been described but is impressively evidenced in this study by frequent co-amplification of the SYK-regulated SPRR1A, SPRR1B, MUC1, RAB25, and ADAM15, genes located within chromosome 1q." (PMID 24523870, 2014). "Furthermore, recent studies have reported the prognostic value of a high expression of SPRR1A in colon cancer, breast cancer and diffuse large B-cell lymphoma." (PMID 35617311, 2022). "A study demonstrated SPRR1A downregulation in MCF-10A breast cancer cells when coculture with CAFs." (PMID 35768785, 2022). "The expression of SPRR1A is not usually found in normal non-squamous tissues, and its increased expression has been reported in some types of non-squamous cell carcinoma (non-SCC), such as colorectal cancer and breast cancer." (PMID 35617311, 2022).
myocardial infarction (4 papers, 2023 to 2025). Gross necrosis of the myocardium, as a result of interruption of the blood supply to the area, as in coronary thrombosis. "Previous studies have shown that Sprr1a overexpression promotes cardiac fibrosis/apoptosis while its knockdown alleviates these effects, particularly after myocardial infarction (MI) or ischemia/reperfusion injury." (PMID 41432818, 2025). "We previously reported that miR-150 is protective during myocardial infarction (MI) in part by decreasing cardiomyocyte (CM) apoptosis and that proapoptotic small proline-rich protein 1a (Sprr1a) is a direct CM target of miR-150." (PMID 37468478, 2023). "The knockout of Sprr1a in mice can improve cardiac dysfunction after myocardial infarction, and the expression of Sprr1a in colorectal cancer tissues is significantly increased, which may be used as a potential biomarker for the prognosis of colon cancer." (PMID 40766079, 2025).
colorectal cancer (3 papers, 2017 to 2025). A primary or metastatic malignant neoplasm that affects the colon or rectum. "Higher expression of Sprr1a is also observed both in the colonic mucosa of mice fed with a folate-deficient diet and in the normal tissue of patients with colorectal cancer compared to that of controls." (PMID 28170448, 2017).
diffuse large B-cell lymphoma (3 papers, 2014 to 2022). "In the present study, we assessed the potential prognostic value of SPRR1A expression in 967 patients with diffuse large B-cell lymphomas." (PMID 24886019, 2014). "SPRR1A expression may be useful as a prognostic factor for diffuse large B-cell lymphoma." (PMID 24886019, 2014).
ischemia (3 papers, 2021 to 2024). A hypoperfusion of the BLOOD through an organ or tissue caused by a PATHOLOGIC CONSTRICTION or obstruction of its BLOOD VESSELS, or an absence of BLOOD CIRCULATION. "Our studies further reveal that Sprr1a expression is upregulated in CMs isolated from ischemic myocardium and subjected to simulated ischemia/reperfusion, while its expression is downregulated in hearts and CMs by Carv." (PMID 34403363, 2021). "Although we show that modulating the miR-150/SPRR1A axis affects HCF activation after H/R, most CFs are activated by recruited inflammatory cells after MI, not by ischemia." (PMID 37468478, 2023).
lung carcinoma (3 papers, 2021 to 2024). "The S100A6 protein, which was found to be an interacting partner of SPRR3 and SPRR1A in KLK6 high group, has been associated with cells motility and tumor metastasis in cervical cancer cells and lung carcinoma." (PMID 34065672, 2021).
colon cancer (2 papers, 2022 to 2025). "High expression of SPRR1A was reported to be associated with poor survival in colon cancer patients." (PMID 36293321, 2022). "SPRR1A was recently proposed as a prognostic marker of colon cancer as its expression was higher in tumors compared to the adjacent noncancerous tissues." (PMID 36293321, 2022).
pancreatic cancers (2 papers, 2021 to 2022). "The transcript levels of SPRR1A in pancreatic cancers were elevated in 89 of 177 cases and were significantly higher than in normal pancreatic tissues (mean TPM 1.28 vs. 45.99, p < 0.0001)." (PMID 35617311, 2022). "In TCGA analyses, we stratified 177 patients with pancreatic cancers by the transcript level of SPRR1A into three groups." (PMID 35617311, 2022). "To assess the expression of SPRR1A in pancreatic cancers, we initially compared the transcript levels of SPRR1A between normal pancreas tissues and pancreatic cancers by analyzing RNA sequencing data from two databases (TCGA and GTEx)." (PMID 35617311, 2022). "When we examined the expression of SPRR1A in various pancreatic cancer cell lines, including PK-1, some lines (KLM-1, Panc-1 and MIAPaca2) did not express SPRR1A." (PMID 35617311, 2022). "To examine whether or not SPRR1A overexpression leads to aggressive behavior in PDAC, we initially used PK-1, a well-differentiated PDAC, which is the most common pancreatic cancer, and generated a stable line by overexpressing SPRR1A using retroviral vectors." (PMID 35617311, 2022). "Furthermore, we overexpressed SPRR1A in pancreatic cancer cell lines (PK-1 and Panc-1) and assessed the phenotype and gene expression changes in vitro." (PMID 35617311, 2022).
acute myeloid leukemia (1 paper, 2023). Acute myeloid leukemia (AML) is a group of neoplasms arising from precursor cells committed to the myeloid cell-line differentiation. "Additionally, some marker genes, such as SPRR1A in acute myeloid leukemia (LAML) and DEFA in uveal melanoma (UVM), have low expression levels in some cancers, revealing how marker genes can provide more relevant information." (PMID 37717102, 2023).
atopic dermatitis (1 paper, 2021). "We found that the mRNA expression of SPRR1A and 2C was upregulated in atopic dermatitis-related skin lesions." (PMID 33452236, 2021).
autosomal-recessive exfoliative ichthyosis (1 paper, 2022). "Mutation of ALOX12B and/or SPRR1A may result in skin barrier-related diseases, such as psoriasis and autosomal-recessive exfoliative ichthyosis." (PMID 35768785, 2022).
diabetes (1 paper, 2026). "Additionally, markers of keratinization, including Sprr1a, Krt8, and Ivl, were downregulated in the diabetes group but were upregulated following C-dots treatment." (PMID 40154736, 2026).
fibrosis (1 paper, 2023). the formation of excess fibrous connective tissue in an organ or tissue in a reparative or reactive process. "Our current study also demonstrates for the first time that SPRR1A knockdown suppresses HCF proliferation and migration and that Sprr1a knockdown attenuates cardiac fibrosis post-MI observed following miR-150 deletion (, 3)." (PMID 37468478, 2023). "Adenovirus-mediated ectopic overexpression of Sprr1a promoted cardiac fibrosis in vivo after TAC whereas protecting CMs and isolated hearts against 2-deoxyglucose and ex vivo I/R." (PMID 37468478, 2023).
gingivitis (1 paper, 2022). A disorder involving inflammation of the gums; may affect surrounding and supporting structures of the teeth. "This review identified that exRNA has the greatest diagnostic potential, with four biomarkers (SPRR1A, lnc-TET3-2:1, FAM25A, CRCT1) displaying sensitivity of >71% and specificity of 100% in the assessed samples (p < 0.001) for gingivitis." (PMID 35453967, 2022).
infarction (1 paper, 2024). A localised pathological necrosis of tissue resulting from obstruction of the blood supply usually by a thrombus, an embolus, or vascular torsion. "Functional analysis of SPRR1A, a DSC3 interactor, revealed its unique interaction with miRNA during cardiac fibroblast activation upon post-infarction remodeling." (PMID 39457608, 2024).
Insulin resistance (1 paper, 2025). Increased resistance towards insulin, that is, diminished effectiveness of insulin in reducing blood glucose levels. "Sprr1a was also upregulated in db/db mouse islets and in wild-type mice subjected to chemically-induced insulin resistance." (PMID 40950193, 2025).
lymph node metastasis (1 paper, 2022). "SPRR1A expression was positively associated with favorable survival and lower lymph node metastasis in HNSCC patients." (PMID 35768785, 2022).
peripheral nerve injury (1 paper, 2018). Injury to a peripheral nerve. "Additionally, Sprr1a is involved in regeneration and its protein levels are elevated in DRG following peripheral nerve injury." (PMID 30906902, 2018).
pterygium (1 paper, 2021). A wedge-shaped fibrovascular lesion arising from the bulbar conjunctiva and extending to the cornea. "An early microarray study identified SPRR3, SPRR1A, SPRR1B and IVL from the cornification subcategory as upregulated genes in pterygium." (PMID 34769520, 2021).
sickle cell disease (1 paper, 2018). Sickle cell anemias are chronic hemolytic diseases that may induce three types of acute accidents: severe anemia, severe bacterial infections, and ischemic vasoocclusive accidents (VOA) caused by sickle-shaped red blood cells obstructing small blood vessels and capillaries. "In a transcriptomic analysis of human DRG, Sprr1a (small proline-rich protein 1a) was identified as a signature gene associated with pain experienced in sickle cell disease." (PMID 30906902, 2018).
skin infection (1 paper, 2022). An inflammatory process affecting the skin, caused by bacteria, viruses, parasites, or fungi. "Intravital imaging and quantification revealed that Sprr1a−/−;Sprr2a−/− mice are more susceptible to P. aeruginosa skin infection." (PMID 35234613, 2022). "Sprr1a−/−;Sprr2a−/− mice are more susceptible to MRSA and P. aeruginosa skin infection, revealing that SPRR proteins protect against pathogenic bacterial infections of the skin." (PMID 35234613, 2022). "Thus, Sprr1a−/−;Sprr2a−/− mice are more susceptible to MRSA and P. aeruginosa skin infection." (PMID 35234613, 2022). "Given that SPRR1A and SPRR2A proteins exhibited bactericidal activity against a panel of skin pathogens in vitro, we predicted that the removal of these proteins might promote MRSA and P. aeruginosa skin infection in vivo." (PMID 35234613, 2022).
urothelial carcinoma (1 paper, 2022). A malignant neoplasm derived from the transitional epithelium of the urinary tract (urinary bladder, ureter, urethra, or renal pelvis). "In normal squamous epithelial tissues and urothelial carcinoma with squamous differentiation, increased expression of SPRR1A has been reported as a result of terminal squamous cell differentiation." (PMID 35617311, 2022).
virus infection (1 paper, 2022). "Both Akata virus infection and AG876 virus infection decrease the expression levels of numerous different differentiation markers induced by methylcellulose suspension in uninfected NOKs, including K10, involucrin, GHRL3, ZNF750, KLF4, TGM1 and SPRR1A." (PMID 36190982, 2022).
cancer (10 papers, 2014 to 2025). A tumor composed of atypical neoplastic, often pleomorphic cells that invade other tissues. "Cancer cell 2 expressed Sprr1a, Lgals7, and Ifitm1, which are associated with the mesenchymal/basal-like subtype and a poor prognosis in PDAC." (PMID 37998349, 2023). "Downregulated expression of ALOX12B or SPRR1A was associated with poor survival rate and advanced cancer stages." (PMID 35768785, 2022). "In the HPV- HNSCC TCGA database (TIMER2.0 online database), the xCell, EPIC, MCP-counter, and TIDE algorithms showed that downregulation of both hub genes (ALOX12B and SPRR1A) were correlated with increased cancer-associated fibroblasts (CAFs)." (PMID 35768785, 2022). "Notably, the expression of ALOX12B and SPRR1A were negatively correlated with cancer-associated fibroblasts (CAFs) infiltration and CAFs downstream effectors." (PMID 35768785, 2022). "We have also found that SPRR1A may be associated with the characteristics of cancer stem cells derived from osteosarcoma." (PMID 35617311, 2022). "Interestingly, SPRR1A expression was also reported to be inversely linked with survival of cancer patients." (PMID 34403363, 2021). "Notably, SPRR1A expression was inversely associated with the survival of cancer patients." (PMID 37468478, 2023). "SPRR1A downregulation was correlated with advanced N stage and cancer stage in the TCGA final discovery cohort (P = 0.0016) and GSE41613 (P = 0.038), respectively." (PMID 35768785, 2022). "The high-SPRR1A-expression group showed the following two main expression patterns: in well and moderately differentiated carcinoma, SPRR1A was expressed mainly in invasive areas (Case 6), while in poorly differentiated carcinoma, SPRR1A was patchily expressed (Case 3)." (PMID 35617311, 2022). "However, our in vitro study showed that SPRR1A overexpression in both PK-1 (expressing SPRR1A) and Panc-1 (not expressing SPRR1A) did not affect the phenotype, such as cell proliferation, chemo-resistance, EMT and migration ability, all of which are associated with aggressive behavior in cancers." (PMID 35617311, 2022). "It is hypothesised that the levels of SPRR1A and SPRR2A will be altered in the tumour and margin samples from patients with HNSCC, which will reflect their role in the processes of cancer cell proliferation and cancer cell survival." (PMID 40647632, 2025). "SPRR1A and ALOX12B downregulation was observed in HPV16- HNSCC patients at advanced cancer stage." (PMID 35768785, 2022). "We have not evaluated the function of SPRR1A in other types of cancers, but our data suggested that SPRR1A did not induce the activation of cancer growth signaling, at least not in PDAC." (PMID 35617311, 2022). "However, there is no research focusing on the biological features of SPRR1A in cancers nor the expression of SPRR1A in PDAC." (PMID 35617311, 2022). "According to these findings, SPRR1A may involve the pathogenesis of non-SCC, leading to a worse prognosis for cancer patients." (PMID 35617311, 2022).